CTSK (cathepsin K)
Diseases named in the same sentence as CTSK in open-access papers (continued):
Sharing a sentence is not in itself a finding about the gene and the disease.
osteoporosis (continued). "Thus, new targets are being studied for the treatment of osteoporosis, such as cathepsin K inhibitors or anti-sclerostin therapies; however, an ideal osteoporosis therapy has not yet been developed, as they still present considerable adverse effects that limit their long-term use." (PMID 36012730, 2022). "Thus, while the human disease provided an excellent model for the identification of cathepsin K and its importance in bone resorption could not fully predict the effects of cathepsin K inhibition in humans with osteoporosis." (PMID 26892377, 2016). "Expression levels of ALPL, BGLAP, and TNF were not significantly different between control and osteoporosis groups, but those of ACP5 and CTSK were significantly increased in patients with osteoporosis compared to those in the controls." (PMID 37339951, 2023).
pycnodysostosis (54 papers, 2006 to 2025). "Pycnodysostosis is a rare autosomal recessive skeletal dysplasia caused by pathogenic variants in the CTSK gene, which encodes cathepsin K, an enzyme essential for osteoclastic bone resorption." (PMID 41311756, 2025). "Pycnodysostosis is a very rare skeletal dysplasia caused by biallelic loss-of-function mutations in cathepsin K, a proteolytic enzyme highly expressed by osteoclasts." (PMID 40144453, 2025). "Deficiency in this enzyme due to CTSK mutations leads to osteoclast dysfunction, contributing to the sclerotic and fragile bone phenotype observed in pycnodysostosis." (PMID 40313484, 2025). "Pycnodysostosis, a rare osteopetrosis subtype, is mainly caused by homozygous or compound heterozygous biallelic pathogenic mutation of the cathepsin K (CTSK) gene." (PMID 40313484, 2025). "Although pycnodysostosis pathophysiology remains unclarified, studies suggest the involvement of a genetic enzyme encoding CTSK, which disrupts and impairs normal osteoclast-mediated bone resorption, resulting in osteosclerosis." (PMID 40313484, 2025). "These imaging findings reflect impaired bone resorption due to cathepsin K deficiency and help differentiate pycnodysostosis from other sclerosing bone dysplasias." (PMID 41311756, 2025). "The pivotal role of CtsK in bone homeostasis is manifested by a rare human disease called pycnodysostosis, which is caused by loss-of-function mutations of CtsK." (PMID 38260317, 2024). "Pycnodysostosis is a rare autosomal recessive bone disorder caused by mutations in the cathepsin K (CTSK) gene, characterized by increased bone density, short stature, and skeletal fragility." (PMID 39421125, 2024). "There are more than 35 CTSK variants associated with pycnodysostosis; the proband in this report has a known pathogenic variant, c.953G > A (p.Cys318Tyr)." (PMID 37288425, 2023). "In cathepsin K deficient state such as pycnodysostosis, the degradation of several matrix-embedded growth factors, including IGF-I, were prevented." (PMID 37809147, 2023). "Located on 1q21, biallelic pathogenic loss of function mutations of cathepsin K gene (CTSK) leads to pycnodysostosis." (PMID 37809147, 2023). "Individuals with pycnodysostosis are deficient in cathepsin K. Although the number of osteoclasts is normal, they are functionally insufficient and organic bone matrix proteins secreted during resorption cannot be degraded properly." (PMID 37809147, 2023). "Calvaria thickening is also observed in cases of pyknodysostosis, a rare autosomal recessive bone dysplasia caused by mutations in CTSK (cathepsin K), characterized by osteosclerosis and short stature." (PMID 36225206, 2022). "The current study presents the largest cohort of pycnodysostosis in Egyptian patients, thoroughly discussing variable presentations, complications, and molecular pathology with a report of three novel CTSK disease-causing variants." (PMID 34680947, 2021). "Pycnodysostosis is caused by defective enzymatic degradation of organic bone matrix, due to autosomal recessive mutations in the gene encoding cathepsin K. Secreted by osteoclasts, cathepsin K cleaves type I collagen." (PMID 34539568, 2021). "Inactivation of CTSK by mutations in the Ctsk gene are further associated with increased bone density (osteopetrosis) in pycnodysostosis, an inheritable condition marked by skeletal abnormalities." (PMID 33592138, 2021). "Pycnodysostosis, a rare autosomal recessive skeletal dysplasia, is due to loss-of-function mutations of the cathepsin K gene and is characterized by short stature, osteosclerosis, acroosteolysis of the distal phalanges, and increased bone fragility." (PMID 33670411, 2021). "Pycnodysostosis, a rare autosomal recessive skeletal dysplasia, is caused by a deficiency of cathepsin K. Patients have impaired bone resorption in the presence of normal or increased numbers of multinucleated, but dysfunctional, osteoclasts." (PMID 33670411, 2021).
pycnodysostosis (continued). "Homozygous or compound heterozygos variants in the CTSK gene are known to cause Pyknodysostosis (MIM# 601105)." (PMID 32883051, 2020). "Equally the discovery of CTSK (cathepsin) as the cause of pycnodysostosis has led to the development of a new class of bone resorptive drugs; CTSK inhibitors, which have been trialled for osteoarthritis." (PMID 31888683, 2019). "Pycnodysostosis is an autosomal recessive disorder due to loss-of-function mutations of the CTSK gene encoding the cysteine protease cathepsin K, which is responsible for degradation of collagen type I and other bone proteins." (PMID 31514440, 2019). "Pycnodysostosis is an autosomal recessive metabolic bone disorder caused by mutations in the cathepsin K (CTSK) gene." (PMID 30209646, 2018). "Patients with pycnodysostosis, a disorder caused by inactivating mutations in the cathepsin K gene, exhibit abnormally dense bone (osteopetrosis), and this effect is reproduced in transgenic mice that are deficient in cathepsin K." (PMID 29523155, 2018). "This is reflected by the lack of bone resorption and the high bone mass phenotype in cathepsin K-deficient mice and in pycnodysostosis patients, who lack functional cathepsin K due to various inactivating mutations in the cathepsin K gene." (PMID 29743078, 2018). "On the other hand, patients with pycnodysostosis caused by mutations of the CTSK gene displayedmultipledental abnormalities, such as hypoplasia of the enamel, obliterated pulp chambers, hypercementosis and periodontal disease." (PMID 28095448, 2017). "In clinical genetic studies, mutations in the CTSK gene have been found to cause pycnodysostosis,an autosomal recessive bone disease (OMIM 265800)." (PMID 28095448, 2017). "The present study is the first to report a rare case of the coexistence of pycnodysostosis with a compound CTSK gene mutation and sporadic MTC." (PMID 29390266, 2017). "Pycnodysostosis is a rare autosomal recessive skeletal dysplasia caused by a mutation in the cathepsin K encoded by cathepsin K gene (CTSK)." (PMID 29390266, 2017). "Pycnodysostosis (PDO) is a rare genetic disorder characterized by cathepsin K deficiency which plays an important role in bone metabolism." (PMID 29318055, 2017). "In conclusion, the present study is the first to report a rare case of the coexistence of pycnodysostosis with novel CTSK gene mutation and sporadic MTC." (PMID 29390266, 2017). "Though enamel phenotypeswere not yet describedin Ctsk knockout mice, enamel hypoplasiawas frequently reported in patients with pycnodysostosis due tovarious CTSK mutations." (PMID 28095448, 2017). "These authors also provided further evidence that cathepsin K deficiency causes pycnodysostosis by finding additional mutations in two unrelated Mexican and American-Hispanic families." (PMID 26892377, 2016). "Mutations in the cathepsin K gene are linked to pycnodysostosis, an autosomal recessive osteochondrodysplasia characterised by osteosclerosis, bone fragility and decreased bone turnover." (PMID 26634933, 2016). "Deficiency of cathepsin K in humans, as it occurs in pycnodysostosis, is associated with high BMD but also increased bone fragility in about half of the patients." (PMID 26892377, 2016). "Sequencing of the CTSK gene in several individuals with a suggestive phenotype of pycnodysostosis has provided evidence for mutations in this gene." (PMID 27558267, 2016). "In this study, the coding region and exon/intron boundaries of the CTSK gene were analyzed for mutations in sixteen children from fourteen families with Pycnodysostosis." (PMID 24767306, 2014). "In this study, we identified seven different homozygous CTSK mutations in sixteen Turkish children with pycnodysostosis from 14 families." (PMID 24767306, 2014). "We detected homozygous mutation in the CTSK gene in all patients diagnosed as pycnodysostosis by clinical features." (PMID 24767306, 2014).
pycnodysostosis (continued). "The human disease pycnodysostosis that occurs due to mutations in cathepsin K gene have a phenotype similar with the knockout mice." (PMID 25010555, 2014). "In conclusion, analyses of the CTSK gene in our pycnodysostosis cohort resulted in the description of five novel mutations including one large insertion in the CTSK gene, with a possible founder effect." (PMID 24767306, 2014). "The gene locus responsible for the Pycnodysostosis had been mapped to human chromosome 1q21 by genetic linkage analysis and the gene encoding cathepsin K (CTSK) was identified through the positional cloning strategy." (PMID 24767306, 2014). "Mutations in the CTSK gene cause a rare autosomal recessive bone disorder called pycnodysostosis (OMIM 265800)." (PMID 21569238, 2011). "The coexistence of increased bone density in long bones (osteosclerosis) and osteolysis in the distal phalanges and calvariae is a typical characteristic of pycnodysostosis with CTSK mutation." (PMID 21569238, 2011). "We describe a missense mutation in the CTSK gene in a Pakistani family affected with autosomal recessive pycnodysostosis." (PMID 19674475, 2009). "Pycnodysostosis is a lysosomal storage disease of the bone caused by a mutation in the gene that codes the enzyme cathepsin K. The syndrome has been frequently reported in history." (PMID 19829823, 2009). "In humans, inactivating mutations in the cathepsin K gene are associated with an osteoclast resorbing defect manifest by pycnodysostosis." (PMID 16613614, 2006). "The gene responsible for pycnodysostosis is CTSK, locatedon chromosome 1 (1q21), encoding cathepsin K, apapain superfamily cysteine peptidase used by osteoclaststo degrade bone matrix and endowed with the uniqueability to cleave collagen molecules in multiple sites." (PMID 37465191, 2023). "CTSK is predominantly expressed in osteoclasts, mutations of which lead to pycnodysostosis." (PMID 36671556, 2023). "Cathepsin-K gene mutation analysis confirmed the diagnosis of pycnodysostosis." (PMID 32248673, 2020). "In 1995, Gelb and colleagues performed a genome-wide search in a large consanguineous Israeli Arab family with 16 affected individuals, identified the locus of pycnodysostosis to chromosome 1q21, and found a mutation in the gene encoding cathepsin K by positional cloning." (PMID 26892377, 2016). "Genetically, cathepsin K gene mutations were found in patients with pycnodysostosis." (PMID 26448892, 2015). "Thirty three different CTSK mutations have been found in 59 unrelated pycnodysostosis families." (PMID 21569238, 2011). "The present findings of an increased resorbed bone area in the presence of E64 correlate well with in vivo findings in mice, as well as in patients with pycnodysostosis, arising from cathepsin K deficiency, where demineralized areas are observed below the osteoclasts." (PMID 20515459, 2010). "Additionally, osteopetrosis may be secondary to the bone pathology arising from cathepsin K (CTSK) mutations, which is termed pycnodysostosis in humans." (PMID 33970241, 2021). "Interestingly, inhibition of cathepsin K by a broad-spectrum cysteine proteinase inhibitor induced unusual features at the reversal phase in a mouse model, and similar observations were made in a rabbit model and in pycnodysostosis, a disease caused by a mutation in the gene encoding cathepsin K." (PMID 24085265, 2014). "Pycnodysostosis (PYCD) is an uncommon hereditary skeletal disorder inherited in an autosomal recessive pattern, caused by mutations that result in a deficiency of the enzyme cathepsin K (CTSK)." (PMID 41185790, 2025). "Pycnodysostosis (PKND, OMIM ID: 265800) is an autosomal recessive LSD mainly affecting skeletal structures caused by mutations in the gene encoding CTSK." (PMID 32326609, 2020). "Defects in CTSA, CTSD, CTSF, and CTSK result in galactosialidosis, neuronal ceroid lipofuscinoses (NCLs) type 10 and type 13, and pycnodysostosis, respectively." (PMID 32326609, 2020).
pycnodysostosis (continued). "In particular, lack of CtsK function was associated to bone-related conditions such as osteopetrosis and the autosomal recessive gene disorder, pycnodysostosis, whereas overexpression of CtsK was reported in metastatic cancer cells." (PMID 32188406, 2020). "Pycnodysostosis is caused by mutations in the CTSK gene located on chromosome 1q21 encoding a lysosomal cysteine protease, cathepsin K, which is widely expressed in bone, ovary, heart, placenta, lung, skeletal muscle, colon, and small intestine." (PMID 29390266, 2017). "Our resultsshed lights on revealing new functions of CTSK and pathogenesis of pycnodysostosis in oral tissues." (PMID 28095448, 2017). "In line with these actions of cathepsin K and consistent with the histological findings, patients with pycnodysostosis have normal serum TRAP5b values, a marker of osteoclast number, while serum NTX and CTX values are low and those of serum 1CTP are increased." (PMID 26892377, 2016). "Pycnodysostosis, marked by high bone mass, short stature, skull deformities and acroosteolysis, is caused by mutations in CTSK encoding cathepsin K, an enzyme secreted by osteoclasts and crucial to bone resorption." (PMID 27533615, 2016). "If the role of CTSK in the human immune system is confirmed, it will be helpful in further understanding of the mechanism of pycnodysostosis and in designing specific treatment strategies." (PMID 21569238, 2011). "More detailed information about the clinical and genetic characteristics in pycnodysostosis patients are necessary for the further research to elucidate the CTSK genotype-phenotype correlation." (PMID 21569238, 2011). "In order to determine CTSK expression, monocyte-derived macrophages were isolated from the peripheral blood of 2 siblings suffering from pycnodysostosis and their unaffected parents." (PMID 21569238, 2011). "The candidate gene for pycnodysostosis was mapped to human chromosome 1q21 by genetic linkage analysis, and was subsequently identified as coding for cathepsin K (CTSK, MIM# 601105) by a positional cloning strategy in 1996." (PMID 21569238, 2011). "It is, noteworthy that cathepsin K is also crucial for callus maturation and remodeling, and the lack of the enzyme does very likely contribute to impaired and/or delayed fracture healing and refracture in patients with pycnodysostosis." (PMID 40144453, 2025). "In addition, deletion of the CtsK gene in mouse resulted in severe osteopetrosis phenotype similar to what is observed in pycnodysostosis." (PMID 38260317, 2024). "The absence of cathepsin K activity in humans due to a CTSK mutation results in pycnodysostosis, a rare bone disease characterized by osteosclerosis and fractures." (PMID 35966102, 2022). "First described in 1962 and said to be the malady of both Toulouse-Lautrec and Aesop (known for his fables), pycnodysostosis (MIM265800) is caused by defective enzymatic degradation of organic bone matrix, due to an autosomal recessive mutation in CATK (coding for cathepsin K)." (PMID 33193107, 2020). "Similarly, genetic dissection of pycnodysostosis led to the development of Cathepsin K inhibitors and the first-in-class agent (odanocatib), successful in phase 3 and extension trials but disappointingly not taken forward into clinical practice." (PMID 33193107, 2020). "This has previously been observed in a RA patient with concomitant pycnodysostosis, an autosomal recessive mutation in the cathepsin K gene characterized by absence of this enzyme." (PMID 28286757, 2017). "This patient with cathepsin K deficiency had typical phenotypic, radiographic, and histological features of pycnodysostosis but she had never experienced a fragility fracture." (PMID 26892377, 2016). "Further studies of patients with pycnodysostosis confirmed these original findings and revealed the presence of at least 35 different mutations in the cathepsin K gene with no, however, clear genotype-phenotype associations." (PMID 26892377, 2016).
pycnodysostosis (continued). "This high frequency of pycnodysostosis prompted us to perform a molecular investigation of the CTSK gene in these families to evaluate the hypothesis of a possible founder effect." (PMID 27558267, 2016). "In order to follow the advances in the research about CTSK and pycnodysostosis, we performed a literature retrospective study of 159 pycnodysostosis patients reported since 1996 and focused on the genetic characteristics of CTSK mutations and/or the clinical phenotypes of pycnodysostosis." (PMID 21569238, 2011). "Cathepsin K-deficient mice generated by targeted inactivation of the CTSK gene display an osteopetrotic phenotype, and their ultrastructural, histological, and radiological abnormalities closely resemble those described for pycnodysostosis." (PMID 19674475, 2009). "Genotyping results showed linkage of the pycnodysostosis Pakistani family to the CTSK locus." (PMID 19674475, 2009). "Pycnodysostosis is caused by a gene that was not discovered until 1995 when relevance analysis studies found on chromosome 1q21, which causes a mutation in cathepsin K, a lysosomal cysteine protease that is highly expressed in osteoclasts, leading to osteosclerosis and impaired bone resorption." (PMID 36381044, 2022). "All of these methods, including isolation of monocytes from the pycnodysostosis patients and transfection in COS-7 cells, 293 cells, and P. pastoris GS115 cells, demonstrated that CTSK mutants are functionally different from the wild type." (PMID 21569238, 2011). "Features that differentiate pycnodysostosis from CCD are acro-osteolysis, bone sclerosis with tendency to fracture, absence of supernumerary teeth, and cathepsin K (CTSK) gene mutations." (PMID 34737766, 2021). "Lack of cathepsin K results in pycnodysostosis, a disease characterized by high bone mass and skeletal deformities." (PMID 20515459, 2010). "Collagen leftover might be partially degraded by other proteases that are upregulated as a compensatory mechanism to counteract the lack of cathepsin K and bone turnover of patients with pycnodysostosis is maintained to a certain extent or even increased." (PMID 40144453, 2025). "Increased expression of cathepsins L and S in osteoclasts derived from the lactating patient suggests that other proteinases could compensate for the lack of cathepsin K during the lactation period of pycnodysostosis patients." (PMID 33670411, 2021). "In addition, lack of a skeletal phenotype in heterozygote carriers of pycnodysostosis indicates that the degree of life-long inhibition of cathepsin K may be important." (PMID 26892377, 2016). "There might be an additional role for osteocyte-mediated degradation of bone matrix in the absence of cathepsin K. Based on the in vitro results, it is unlikely that cathepsin K-deficient osteoclasts were the only source of the increased levels of CTX in our lactating patient with pycnodysostosis." (PMID 33670411, 2021).